PRMT1 (protein arginine methyltransferase 1)
Diseases named in the same sentence as PRMT1 in open-access papers (continued):
Sharing a sentence is not in itself a finding about the gene and the disease.
diabetes (7 papers, 2015 to 2025). "This research also validated the findings of Choi and colleagues that a deficiency in PRMT1 alleviated diabetic hyperglycemia, providing further evidence that PRMT1 is a promising research topic in the diabetes research field." (PMID 40001488, 2025). "As such, numerous PRMT1 inhibitors have been developed that display promising anti-cancer and anti-diabetes properties in cell lines and animal models." (PMID 40001488, 2025). "Not only the miRNA miR-574-3p showed an interesting interaction with PRMT1 in the context of diabetes." (PMID 40001488, 2025). "In this case, dysfunction of PRMT1 is most prominently translated into diabetes—specifically, type 2 diabetes." (PMID 40001488, 2025). "The PRMT1‐v2–PGC‐1α regulatory axis is markedly induced by fasting and diabetes, thus representing a key mechanism underlying elevated blood glucose levels in these pathological states." (PMID 41256732, 2025). "Taken together, all this evidence suggests that PRMT1 is an interesting target in diabetes treatment." (PMID 40001488, 2025). "Aberrant expression of PRMT1 is found in many types of cancers, pulmonary diseases, cardiovascular disease, diabetes, and renal diseases." (PMID 29535867, 2018). "Understanding the influence of PRMT1 on the first stages of development may be the key to elucidating the finer details of the pathogenesis of diabetes." (PMID 40001488, 2025). "Knockout of the Prmt1 gene in β-cells induced diabetes in both fetal and adult mice." (PMID 40001488, 2025). "Their research revealed that PRMT1 plays a major role in the pathogenesis of diabetes." (PMID 40001488, 2025). "Metabolic conditions such as diabetes alter the expression of the protein arginine N-methyltransferase 1-asymmetric dimethylarginine-dimethylarginine dimethylamino-hydrolase (PRMT1-ADMA-DDAH) axis where adversely higher ADMA expression will result in higher PRMT1 and lower DDAH1 expressions." (PMID 37627550, 2023). "Murine models of diabetes, established through a HFD or streptozotocin administration, exhibit significant upregulation of the hepatic PRMT1‐v2 isoform." (PMID 41256732, 2025). "To confirm the increase of PRMT1 and PRMT4 expression in vivo, we generated rats with streptozotocin- (STZ-) induced diabetes, which show severe hyperglycemia and are known to have induced diabetic retinopathy via oxidative stress." (PMID 26583059, 2015).
endothelial dysfunction (7 papers, 2013 to 2025). In vascular diseases, endothelial dysfunction is a systemic pathological state of the endothelium (the inner lining of blood vessels) and can be broadly defined as an imbalance between vasodilating and vasoconstricting substances produced by (or acting on) the endothelium. "The decline in PRMT1 was strongly associated with endothelial dysfunction, a key factor in COPD progression." (PMID 40135804, 2025). "To gain insights into the importance of NF‐κB signaling in endothelial dysfunction triggered by PRMT1 inhibition, we examined the nuclear localization of p65/NF‐κB in response to furamidine and TNF‐α treatment by immunostaining and nuclear fractionation." (PMID 40135804, 2025). "Increased ADMA levels can result in endothelial dysfunction, irregular vascular tone, and atherosclerosis, thereby establishing PRMT1 as a significant target in cardiovascular disease (CVD) research." (PMID 41256732, 2025). "These alterations correlated with increased macrophage infiltration and endothelial dysfunction, further implicating PRMT1 as a regulator of vascular homeostasis." (PMID 40135804, 2025). "By suppressing NF‐κB activation and preventing inflammatory shifts, PRMT1 protects against endothelial dysfunction, inflammation, and senescence in COPD." (PMID 40135804, 2025). "Acute inhibition of PRMT1 amplified TNF‐α‐induced endothelial dysfunction and senescence via NF‐κB activation, while inhibition of NF‐κB mitigated these effects." (PMID 40135804, 2025). "PRMT1 facilitates damage in LPS‐induced endothelial dysfunction by augmenting protein arginine methylation, elevating ADMA levels, suppressing NO generation, advancing cell senescence, and activating inflammatory pathways." (PMID 41256732, 2025). "PRMT1 as a critical regulator of pulmonary EC function, preventing NF‐κB‐driven endothelial dysfunction and senescence is highlighted here." (PMID 40135804, 2025). "Taken together, these data suggest that PRMT1 is required for suppression of endothelial dysfunction and senescence induced by TNF‐α." (PMID 40135804, 2025). "In the mice model, the administration of high-dose AEC showed improved lipid and blood glucose profiles and a reduction in endothelial dysfunction markers (PRMT-1 and ADMA)." (PMID 36839268, 2023). "Thus, Prmt1 inhibition seems to be a good strategy to treat vascular diseases related to endothelial dysfunction." (PMID 34635781, 2021). "This chapter will methodically examine the precise role and molecular mechanism of PRMT1 in a cardiac‐specific deletion model, myocardial hypertrophy, VSMC function, and endothelial dysfunction." (PMID 41256732, 2025). "In conclusion, the overactivation of PRMT1 in endothelial cells primarily results in a decrease in NO, increased oxidative stress, and exacerbated inflammation through both ADMA‐dependent and independent mechanisms, thus forming the pathological foundation of endothelial dysfunction." (PMID 41256732, 2025). "The results suggest that salt, independent of blood pressure, can affect the PRMT-1/ADMA/DDAH system to a certain degree and lead to endothelial dysfunction in Dahl salt-sensitive rats." (PMID 23584024, 2013).
Hyperglycemia (7 papers, 2015 to 2025). An increased concentration of glucose in the blood. "Conversely, hepatocyte‐specific deletion of PRMT1 attenuates gluconeogenesis and ameliorates hyperglycemia, confirming its pathogenic role." (PMID 41256732, 2025). "Goto-Kakizaki rats exhibited enzymatic impaired PRMT1 activity and defective protein methylation when stimulated by postprandial hyperglycemia, indicating the potential involvement of protein methylation in mediating insulin secretion." (PMID 35087408, 2021). "TC-E was one of the chemicals developed to specifically inhibit PRMT1 activity and has been used to study the role of PRMT1 in myogenesis and hyperglycemia." (PMID 32357521, 2020). "For instance, PRMT1 promotes hyperglycemia by methylating the transcriptional factor forkhead box O1 (FOXO1) and thus increasing its nuclear retention and the transcriptional activity." (PMID 31284549, 2019). "Thus, PRMT1, specifically the PRMT1V2 isoform, promotes the pathogenesis of NAFLD by methylating key transcriptional regulators such as PGC‐1α and FOXO1, thereby augmenting hepatic gluconeogenesis and exacerbating hyperglycemia." (PMID 41256732, 2025).
acute megakaryocytic leukemia (5 papers, 2015 to 2025). "PRMT1 expression is upregulated in acute megakaryocytic leukemia to enhance the usage of glucose for extra nutrients in the cancerous cells, and PRMT1 expression reduces fatty acid oxidation." (PMID 40001488, 2025). "We observed that a specific acute megakaryocytic leukemia (AMKL) cell line (6133) derived from RBM15-MKL1 knock-in mice exhibited heterogeneity in Prmt1 expression levels." (PMID 40801789, 2025). "Overexpression of PRMT1 in acute megakaryocytic leukemia cell lines blocks megakaryocyte terminal differentiation by downregulation of RBM15 protein level." (PMID 26575292, 2015). "Targeting PRMT1 may be a curative therapy to restore megakaryocyte differentiation for acute megakaryocytic leukemia." (PMID 26575292, 2015). "In acute megakaryoblastic leukemia, the protein arginine methyltransferase 1 (PRMT1) is highly expressed and can methylate R578 residue on RBM15 and promotes PRMT1 ubiquitination-mediated degradation by E3 ligase (CNOT4)." (PMID 32653017, 2020). "Recent studies have shown that RNA binding protein RBM15 could be methylated by PRMT1, which resulted in RBM15 degradation via ubiquitylation and retardation of megakaryocyte differentiation in acute megakaryocytic leukemia (AMKL)." (PMID 37558663, 2023).
bladder cancer (5 papers, 2015 to 2023). "We here demonstrate that a protein arginine methyltransferase PRMT1, which are overexpressed in various types of cancer including lung and bladder cancer, methylates arginine 887 in an Aurora Kinase B (AURKB)-binding region of INCENP both in vitro and in vivo." (PMID 26460953, 2015). "We previously reported that PRMT1 was overexpressed in various types of cancer including lung and bladder cancers, and knockdown of PRMT1 resulted in the growth suppression of cancer cells." (PMID 26460953, 2015). "When PRMT1 and PRMT6 genes were knocked down, the growth of bladder cancer cell lines (SW780 and RT4) was significantly inhibited, and the cells in the S phase were significantly reduced, while those in G0 and G1 phases were increased simultaneously." (PMID 35311114, 2022). "Meanwhile, real-time quantitative RT-PCR analysis of gene microarray data suggested that PRMT1 and PRMT6 could lead to the carcinogenesis of bladder cancer by regulating RNA processing and DNA replication." (PMID 35311114, 2022). "Therefore, PRMT1 and PRMT6 may be a promising target for bladder cancer therapy, and their inhibitors may be ideal candidates for molecular targeted therapy of bladder cancer." (PMID 35311114, 2022).
dilated cardiomyopathy (5 papers, 2018 to 2023). Cardiomyopathy which is characterized by dilation and contractile dysfunction of the left and right ventricles. "Cardiac PRMT1 null mice exhibit a sudden death with dilated cardiomyopathy, likely caused by CaMKII dysregulation." (PMID 30504773, 2018). "Since PRMT1-deficient heart caused dilated cardiomyopathy accompanied by cardiomyocyte death, PRMT1 might be important for cardiomyocyte survival." (PMID 31787756, 2019). "Based on these data, we hypothesized that cardiac dysfunction and dilated cardiomyopathy in PRMT1-deficient mice might be due to enhanced CaMKII activity." (PMID 30504773, 2018). "Similar to the cullin-1 substrate adapter Fbxo40, hearts of mice that lack Prmt1 suffer from dilated cardiomyopathy and show aberrant Asb2 splicing." (PMID 33114658, 2020). "Cardiac specific Prmt1 knockouts develop a severe form of dilated cardiomyopathy, accompanied by a previously uncharacterized splice isoform of Fbxo40." (PMID 33114658, 2020). "Cardiac PRMT1 null mice exhibit dilated cardiomyopathy and contractile dysfunction within 2-months." (PMID 30504773, 2018).
Hepatic steatosis (5 papers, 2022 to 2025). Steatosis is a term used to denote lipid accumulation within hepatocytes. "Subsequent research has revealed that downregulating PRMT1 intensifies hepatic steatosis in mice, whereas overexpressing wild‐type PRMT1 alleviates liver fat accumulation caused by a HFD." (PMID 41256732, 2025). "Supporting this model, PRMT1 knockdown in methionine‐choline deficient diet‐induced NAFLD models significantly ameliorates hepatic steatosis and reduces TG content." (PMID 41256732, 2025). "Fascinatingly, a DisGeNET database analysis revealed that various metabolic diseases, such as fatty liver disease, drug-induced liver disease, and liver injury, were associated with PRMT1 as well." (PMID 40001488, 2025). "To conclude, these findings collectively suggest that PRMT1 deficiency promotes the development of hepatic steatosis and liver injury in mice." (PMID 35401831, 2022). "Concurrently, PRMT1 modulates lipid metabolic pathways, further driving hepatic steatosis and disease progression." (PMID 41256732, 2025). "Recently, a study on the impact of PRMT1 on hepatic steatosis revealed that induction of PRMT1 relieved diet-induced hepatic steatosis in both obese mouse models and obese human patients." (PMID 40001488, 2025). "Genes coexpressed with PRMT1 participate in fatty acid metabolism and are prevalent in fatty liver disease and drug‐induced hepatic disorders." (PMID 41256732, 2025). "We demonstrated that overexpression of hepatic PRMT1 in HFD-fed mice for 9-week alleviated hepatic steatosis by enhancing FAO in their livers." (PMID 35401831, 2022). "In summary, we uncover the protective role of hepatic PRMT1 against liver steatosis in obese subjects by induction of hepatic fatty acid oxidation via HNF-4α and PGC-1α dependent mechanism." (PMID 35401831, 2022). "Overexpression of PRMT1-WT consistently showed protective effects against diet-induced hepatic steatosis." (PMID 35401831, 2022). "The role of this predominant protein arginine methyltransferases PRMT1 in hepatic steatosis remains poorly defined." (PMID 35401831, 2022). "Taken together, our results indicate that methyltransferase activity of PRMT1 is indispensable for its protective role against diet-induced hepatic steatosis in mice." (PMID 35401831, 2022). "The dynamic alteration of the expression and methyltransferase activity of PRMT1 in the progression of fatty liver diseases remains elusive." (PMID 35401831, 2022). "To validate the findings above, we further interrogated whether liver-specific overexpression of PRMT1 protects against diet-induced liver steatosis." (PMID 35401831, 2022). "Therefore, we conclude hepatic PRMT1 ameliorate diet-induced hepatic steatosis via induction of PGC-1α expression by methylation of transcription factor HNF-4α." (PMID 35401831, 2022). "Taken together, PGC-1α is required for PRMT1-mediated protective effects against hepatic steatosis." (PMID 35401831, 2022). "In this research, we aimed to discover specifically how PRMT1 regulates hepatic lipid metabolism in obese subjects through comprehensive metabolic phenotyping and deep investigation of molecular mechanisms to enrich our understanding of the role of PRMT1 in hepatic steatosis." (PMID 35401831, 2022). "Currently, more suppression of PRMT1 would diminish HNF‐4α methylation and PGC‐1α transcription, markedly impede fatty acid oxidation, and exacerbate hepatic steatosis." (PMID 41256732, 2025). "Corroborating these findings, diminished expression of both PRMT1 and PGC‐1α in the livers of obese patients correlates with the severity of hepatic steatosis." (PMID 41256732, 2025). "In line with this, another study documented that PRMT1 was found to induce PGC-1α mRNA expression through the recruitment of HNF-4α to the promoter region of PGC-1α, thereby attenuating hepatic steatosis via enhancing PGC-1α-mediated fatty acid oxidation." (PMID 39871927, 2022).
Hepatic steatosis (continued). "Mechanistically, methyltransferase activity of PRMT1 was required to induce PGC-1α mRNA expression via recruitment of HNF-4α to the promoter of PGC-1α, and hence attenuated HFD-induced hepatic steatosis by enhancing PGC-1α-mediated fatty acid oxidation." (PMID 35401831, 2022). "We checked the expression of PRMT1 and PGC-1α in liver biopsies with severe steatosis (n = 8) and those with absence of hepatic steatosis (n = 4) by qPCR and immunostaining analysis." (PMID 35401831, 2022). "Over-expression of wild-type PRMT1, but not methyltransferase-defective mutant PRMT1G80R, could alleviate diet-induced hepatic steatosis." (PMID 35401831, 2022).
liver fibrosis (5 papers, 2023 to 2025). "Consequently, inhibiting PRMT1 may present a viable therapeutic approach for addressing hepatic fibrosis associated with NAFLD." (PMID 41256732, 2025). "Thus, PRMT1 activity may be closely linked to the advancement of liver fibrosis in NAFLD." (PMID 41256732, 2025). "A specific PRMT1 inhibitor, such PT1001B, significantly reduces PRMT1 activity, therefore mitigating hepatic fibrosis in mice." (PMID 41256732, 2025). "The knockout of PRMT1 in the hepatic stellate cells in mice alleviates liver fibrosis by suppressing NF-κB and TGF-β signaling." (PMID 40612681, 2025). "Considering liver fibrosis, PRMT1 is significantly elevated in both hepatocytes and HSCs in the fibrotic liver tissue." (PMID 41256732, 2025). "Hepatic PRMT1 regulates the protein nitrosylation and participates in mediating the progression of alcohol-induced liver fibrosis." (PMID 37627211, 2023). "The results indicate that inhibiting PRMT1 could serve as an effective therapeutic approach for managing liver fibrosis by reducing HSC activation." (PMID 41256732, 2025). "Interestingly, inhibition with the type 1 PRMT inhibitor PT1001B resulted in reduced PRMT1 activity and alleviated liver fibrosis." (PMID 40001488, 2025). "The targeted deletion of PRMT1 in HSCs reduces HSC activation and hepatic fibrosis in the TAA‐induced fibrotic model." (PMID 41256732, 2025).
prostate carcinoma (5 papers, 2017 to 2022). A carcinoma that arises from epithelial cells of the prostate gland. "Notably, prostate cancer was the only cancer type found in our TCGA analysis with low levels of PRMT1, which makes this specific cancer probably more vulnerable for mitochondrial Ca2+ overload." (PMID 29113301, 2017). "Similarly, for prostate cancer, KDM1A, BRD4, and PRMT1 were depleted in LNCaP cells as well as AR, FOXA1 and NCOA1, thus serving as positive controls." (PMID 35973998, 2022).
triple-negative breast carcinoma (5 papers, 2021 to 2025). An invasive breast carcinoma which is negative for expression of estrogen receptor (ER), progesterone receptor (PR), and human epidermal growth factor receptor 2 (HER2). "Inhibition of PRMT1 in triple-negative breast cancer (TNBC) cells triggers an interferon response, leading to cell death, and disrupts chromatin recruitment, enhancing cisplatin efficacy." (PMID 40781072, 2025).
acute lymphoblastic leukemia (4 papers, 2012 to 2023). Leukemia with an acute onset, characterized by the presence of lymphoblasts in the bone marrow and the peripheral blood. "Besides, PRMT1 has been associated with glucocorticoid resistance in acute lymphoblastic leukemia." (PMID 37558663, 2023). "For example, PRMT1-mediated FLT3 arginine methylation exacerbates acute lymphoblastic leukemia progression." (PMID 36151091, 2022).